RNU6-1152P (RNA, U6 small nuclear 1152, pseudogene)
Gene: Small nuclear RNA gene on chromosome 17 (48,196,680 to 48,196,786, reverse strand). Ensembl gene ENSG00000207306.
Homologues: Orthologues: chimpanzee U6 (99% identical), macaque U6 (98% identical), guinea pig U6 (91% identical). Paralogues in human: RNU6-211P (96% identical), RNU6-41P (93% identical), RNU6-820P (93% identical), RNU6-1060P (93% identical), RNU6-116P (93% identical), RNU6-15P (93% identical), RNU6-19P (93% identical), RNU6-35P (93% identical), RNU6-589P (93% identical), RNU6-12P (92% identical), RNU6-13P (92% identical), RNU6-166P (92% identical), and 1286 more.